TDRD12 (tudor domain containing 12)
Description:
Probable ATP-binding RNA helicase required during spermatogenesis to repress transposable elements and preventing their mobilization, which is essential for the germline integrity. Acts via the piRNA metabolic process, which mediates the repression of transposable elements during meiosis by forming complexes composed of piRNAs and Piwi proteins and governs the methylation and subsequent repression of transposons. Involved in the secondary piRNAs metabolic process. Acts via the PET complex, a multiprotein complex required during the secondary piRNAs metabolic process for the PIWIL2 slicing-triggered loading of PIWIL4 piRNAs.
Synonyms: ECAT8; FLJ13072
Tractability: PROTAC: ubiquitination databases record sites on it.
Gene: Protein-coding gene on chromosome 19 (32,719,753 to 32,829,580, forward strand). Ensembl gene ENSG00000173809.
Pathways (Reactome):
Gene expression (Transcription): PIWI-interacting RNA (piRNA) biogenesis
Gene Ontology:
Molecular function: ATP binding; ATP hydrolysis activity; nucleic acid binding; RNA helicase activity
Biological process: fertilization; germ-line stem cell division; male meiotic nuclear division; piRNA processing; spermatogenesis; transposable element silencing by piRNA-mediated DNA methylation
Cellular component: PET complex
Genetic constraint (gnomAD): Loss-of-function variants: 106 observed, 92.2 expected, observed/expected ratio (o/e) 1.15, 90% interval 0.98 to 1.35. The upper end of that interval is the gene's LOEUF score, 1.35, which puts it in group 5 of 6, group 1 being the genes least tolerant of losing a copy. Missense variants: 1,026 observed, 1,020.1 expected, observed/expected ratio (o/e) 1.01, 90% interval 0.95 to 1.06. Synonymous variants: 352 observed, 386.87 expected, observed/expected ratio (o/e) 0.91, 90% interval 0.83 to 0.99.
Homologues: Orthologues: chimpanzee TDRD12 (83% identical), dog TDRD12 (79% identical), rabbit TDRD12 (77% identical), rat Tdrd12 (77% identical), pig TDRD12 (73% identical), mouse Tdrd12 (70% identical), guinea pig TDRD12 (69% identical), zebrafish tdrd12 (36% identical). Paralogues in human: DDX17 (9% identical), DDX10 (9% identical), DDX3Y (9% identical), DDX41 (9% identical), DDX42 (9% identical), DDX3X (9% identical), DDX43 (9% identical), DDX18 (9% identical), DDX24 (9% identical), DDX5 (9% identical), DDX50 (9% identical), DDX59 (9% identical), and 26 more.
Diseases named in the same sentence as TDRD12 in open-access papers:
TDRD12 is named in the same sentence as 9 diseases in open-access papers, as found by Europe PMC text mining. Sharing a sentence is not in itself a finding about the gene and the disease. The quoted sentences say what the papers report.
Infertility (3 papers, 2017 to 2025). "The reduced numbers and eventually loss of the germ cells by 35 days post fertilization (dpf) led to masculinization and infertility of the Tdrd12-deficient fish." (PMID 28590408, 2017). "Interestingly, also humans encode a PIWIL3 protein and we identified one female variant carrier with a homozygous LoF variant in TDRD12, diagnosed with infertility due to premature ovarian insufficiency, a phenotype related to impaired oocyte maturation." (PMID 39122675, 2024). "All Tdrd12-deficient mutants develop as infertile males by 35-dpf exclusively." (PMID 28590408, 2017). "Inactivation of Tdrd12 (or Ecat8) in mice leads to depression of retrotransposons and infertility, indicating the contribution of Tdrd12 in secondary piRNA biogenesis and transposon silencing in the male germline." (PMID 40349219, 2025). "Because maternal Tdrd12 could be inherited from heterozygous parents, as well as the infertility of the homozygous Tdrd12-deficient adults, we have no good indications at present on the roles of maternally provided Tdrd12 at early embryonic stages." (PMID 28590408, 2017).
Azoospermia (2 papers, 2020 to 2023). Absence of any measurable level of sperm,whereby spermatozoa cannot be observed even after centrifugation of the semen pellet. "A novel finding of this study was the link between vitamin D and TDRD12, a gene not previously associated with placental function, although it is known that TDRD12 is important for germ cell function and fertility, and a lower expression of TDRD12 is associated with azoospermia in human males." (PMID 38140291, 2023).
colorectal cancer (1 paper, 2014). A primary or metastatic malignant neoplasm that affects the colon or rectum. "To do this, we selected a small sub-group of these genes that remained transcriptionally silenced in the colorectal cancer cell lines HCT116 and SW480 (ARRDC5, C4orf17, C20orf201, DDX4, NT5C1B, STRA8, TDRD12)." (PMID 25594001, 2014).
Premature ovarian insufficiency (1 paper, 2024). Amenorrhea due to loss of ovarian function before the age of 40. "Interestingly, a sister of M2227, who is also homozygous for the familial TDRD12 stop-gain variant, was affected by impaired fertility due to premature ovarian insufficiency." (PMID 39122675, 2024).
seminoma (1 paper, 2016). A radiosensitive malignant germ cell tumor found in the testis (especially undescended), and extragonadal sites (anterior mediastinum and pineal gland). "DDX43 was heavily methylated in all samples other than seminoma while TDRD12 was methylated in all samples except seminoma and teratoma." (PMID 29263807, 2016). "DDX43 and TDRD12 were specifically hypomethylated in seminoma cells." (PMID 29263807, 2016).
cancer (3 papers, 2016 to 2021). A tumor composed of atypical neoplastic, often pleomorphic cells that invade other tissues. "Although DTA picked genes TDRD9 and TDRD12, which belong to the same family, we found their expression pattern to be quite different for cancer samples." (PMID 34503106, 2021).
TDRD12 also shares sentences with these, for which no sentence is quoted: male infertility (1 paper); Sertoli Cell-Only Syndrome (1); teratoma (1).